MMP12 (matrix metallopeptidase 12)
Diseases named in the same sentence as MMP12 in open-access papers (continued):
Sharing a sentence is not in itself a finding about the gene and the disease.
asthma (42 papers, 2005 to 2025). "This aligns with previous research associating an MMP-12 single nucleotide polymorphism (rs2276109 [−82A→G]) with lung function in individuals with asthma and COPD." (PMID 40940719, 2025). "To address this gap, we investigated the mechanisms of MMP-12 in eosinophilic inflammation-induced fibrosis and associated functional abnormalities using allergen- and IL-13-induced mouse models of asthma." (PMID 40940719, 2025). "Upregulation of MMP12, previously associated with airway remodeling and fibrosis in asthma, also points to potential long-term lung damage." (PMID 41200555, 2025). "Due to ECM-associated activities, MMP12 has an important role in inflammatory diseases such as colitis, asthma, fibrosis, chronic obstructive pulmonary disease (COPD), and cardiovascular disease." (PMID 40362553, 2025). "By using the LASSO algorithm, we identified five shared eosinophil‐associated hub genes (PPP1R14A, FNBP1, DRAM1, FSCN1, and MMP12) in asthma and CC." (PMID 39659035, 2024). "The differentially expressed genes included those related to inflammation (CCL22, CXCL16, AREG, MMP12) involved in asthma pathophysiology, as well as genes associated with the skin barrier (IVL, CDSN, SPINK5, FLG)." (PMID 39451560, 2024). "In sum, their data suggested that the minor allele of a SNP in MMP-12 (rs2276109) is associated with a positive effect on lung function in children with asthma and in adults who smoke." (PMID 35031603, 2022). "MMP12 gene polymorphism is also considered a risk factor for the development of severe asthma in youth." (PMID 34912233, 2021). "In fact, MMP-12 is associated with disease severity in patients with asthma, although the mechanism has not been elucidated." (PMID 34703996, 2021). "MMP1, MMP3, MMP8, and MMP12 levels were associated with severe asthma and were correlated positively with sputum IL-5 levels but negatively with IL-13 levels." (PMID 26851968, 2016). "Shared genetic factors for reduced lung function in children with asthma and adults who smoke (e.g. MMP12 variants) emphasize the role of genetics on long term lung function." (PMID 21699702, 2011). "Thus, the presence of M2 macrophages, as seen in asthma, is important for the activation of MMP-12/neutrophils axis associated with RSV infection." (PMID 34703996, 2021). "Collectively, these results indicated that elevated epithelial SIRT6 promoted IL-17A release, which induced MMPs and cytokines (eg, Mmp3, Mmp12, and Cxcl1) scretion in severe asthma." (PMID 38135684, 2023). "They further demonstrated that TGF-β1 released from eosinophils further induced MMP-2, MMP7, MMP9 and MMP12 which are all essential for abnormal matrix turnover and myofibroblast differentiation in asthma fibrosis." (PMID 36911735, 2023). "Single-nucleotide polymorphisms (SNPs) in the gene encoding MMP-12 is associated with FEV1 in children and adults with severe asthma." (PMID 36078171, 2022). "Prior studies in cockroach and ovalbumin allergen asthma models revealed that MMP12 is a crucial pro-inflammatory response contributor, especially regarding eosinophil recruitment, that can impact structural remodeling allergic airway diseases." (PMID 34912233, 2021). "Regarding asthma, Mmp12 gene knockout mice also exhibit reduced lung inflammation following cockroach antigen-induced asthmatic responses." (PMID 34912233, 2021). "In mice, Mmp12 is modulated throughout the stages of asthma pathology, and its overexpression persists over time." (PMID 34912233, 2021). "Mmp12 plays a role in the extracellular matrix degradation that contributes to airway remodeling in asthma pathogenesis." (PMID 34912233, 2021). "MMP-12 has also been suggested to be connected to the severity of asthma and chronic obstructive pulmonary disease (COPD) and to be involved in the tissue remodeling in these inflammatory respiratory diseases." (PMID 33946872, 2021).
asthma (continued). "In fatal asthma, the expression of MMP-12 increased in airway smooth muscle in large airways compared with that of controls." (PMID 34618857, 2021). "Although MMP-12 is suggested to be involved in asthma, this conclusion is based on studies in which mostly animal models are used." (PMID 31547356, 2019). "Previous studies have shown that the severity of inflammatory responses markedly decreased in MMP9−/− asthma mouse models, and IL-13-induced inflammation reduced upon MMP12 knockdown in mice." (PMID 30250465, 2018). "MMP-12 was previously indentified as a critical mediator of fibrosis in several models of tissue injury, including asthma, chronic obstructive pulmonary disease (COPD) and pulmonary fibrosis." (PMID 25302498, 2014). "The MMP-12 total protein and activity assays were used to assess total protein and activity levels in induced sputum from 18 healthy, 10 asthma, and 10 COPD donors." (PMID 20678199, 2010). "Overproduction of MMP-12 causes pathological ECM protein breakdown and excessive airway remodeling, which has been implicated in a range of respiratory diseases, including asthma and chronic obstructive pulmonary disease (COPD)." (PMID 16359550, 2005). "The smooth muscle cells obtained from normal volunteers showed some expression of MMP-12, but there was elevated expression in the cells obtained from patients with asthma, COPD and chronic cough, however statistical significance was not achieved." (PMID 16359550, 2005). "However, among the collagen degradation biomarkers, C4M (reflecting type IV collagen α1 chain degradation by MMP12) was significantly reduced in individuals with asthma, with a percentage change of −0.05 (p < 0.01)." (PMID 40760731, 2025). "In addition, a study in patients with asthma illustrated that MMP-12 gene variant is associated with disease severity, although no attempt has been made to elucidate the mechanism by which MMP-12 is highly expressed." (PMID 34703996, 2021). "The risk MMP12 gene variant has been reported to be highly related to the severity of asthma in patients and MMP-12 inhibitors may be considered as a potential therapeutic targets of asthma." (PMID 34618857, 2021). "For example, measuring MMP-12 concentrations before and after exacerbation in patients with asthma will clarify whether MMP-12 is a true exacerbating factor." (PMID 34703996, 2021). "Thus, targeting MMP-12 represents a potentially novel therapeutic strategy for the exacerbation of asthma." (PMID 34703996, 2021). "MMP12 has been studied in chronic obstructive pulmonary disease (COPD) and the minor allele of a single nucleotide polymorphism in MMP12 (rs2276109) was associated with a beneficial effect on lung function in smokers and children with asthma." (PMID 33396445, 2020). "Previous studies have implicated MMP12 in the pathogenesis of COPD and asthma." (PMID 27456476, 2016). "We provide evidence that MMP-12 mRNA and protein are expressed by in-situ human airway smooth muscle cells obtained from bronchial biopsies of normal volunteers, and of patients with asthma, COPD and chronic cough." (PMID 16359550, 2005). "As for genetics, it has been found in several cohorts that the minor allele of an SNP in the promoter of the MMP-12 gene (substitution A-to-G at position − 82; rs2276109) is associated both with a reduced risk of developing COPD and with a beneficial effect on lung function in children with asthma." (PMID 39794761, 2025). "In addition, a genetic polymorphism in Mmp12 in humans is associated with COPD and asthma." (PMID 34912233, 2021). "Therefore, the development of therapeutic agents targeting MMP-12 instead of inhaled steroids targeting eosinophils might provide a breakthrough treatment for the exacerbation of asthma or neutrophilic asthma." (PMID 34703996, 2021). "Thus, it is plausible that the in utero SHS exposure-induced increased expression of Mmp12 may contribute to the development of severe asthma." (PMID 34912233, 2021).
asthma (continued). "Asthma-derived eosinophils also stimulated an increased expression of MMP2, MMP-9, MMP-12, TGF-β1 and TGF-β2 in MRC-5 fibroblasts also in correlation with an abnormal matrix turnover and airway fibrosis." (PMID 36911735, 2023). "Some of these HDM-induced effects on single and double-infected cells resulted from aberrant response to HDM in asthma in terms of an increase in IL-33, RGF, TWEAK, MMP12, FTL3G, and M-CSF." (PMID 37087523, 2023). "Compared to air HDM controls, in the HDM-induced asthma model, at 13weeks of age, in utero exposures to SHS increased the percentage of eosinophils in BALF and potentiated Mmp12 gene expression (5.7-fold)." (PMID 34912233, 2021). "The levels of most proteins (ITGAM, ITGB2, MMP12, NCF1, NCF2, NCF4, RAC2 and Vav1) were higher in the asthma condition (shown in red) than those in the control condition or after SCIT condition." (PMID 34618857, 2021). "CLCA1 is also one of the 6 genes (CLCA1, IL4, IL13, MMP12, TGFB1, TLR4) found in common between our KE genesets and the genesets proposed by Bosse24 for COPD and Poole27 for asthma." (PMID 33731770, 2021). "In the HDM-induced asthma model, in utero exposures to SHS produced eosinophilic lung inflammation and potentiated Mmp12 gene expression (5.7-fold compared to air-HDM controls)." (PMID 34912233, 2021). "Corticosteroids are anti-inflammatory drugs used for the treatment of asthma and COPD, and previous studies have shown their inhibitory effects on MMP-12 induction by lipopolysaccharide in human alveolar macrophages." (PMID 16359550, 2005). "MMP-12 mRNA expression was found in ASMC obtained from normal subjects, and was somewhat higher in patients with asthma, COPD and chronic idiopathic cough." (PMID 16359550, 2005). "We investigated whether MMP-12 contributes to eosinophilic inflammation-induced EMT, a process that leads to bronchial fibrosis, in a mouse model of experimental asthma." (PMID 40940719, 2025). "OS biomarkers MDA, FRAP, protein carbonyls, and peroxynitrite, and inflammation biomarkers ILC2/3, MMP-12, CXCL8, neutrophil elastase, AZU-1, and PPBP were found to associate with asthma in smokers, but not in nonsmokers." (PMID 37367073, 2023). "The SNPs in the MMP-12 promoter region increase MMP-12 expression, which may activate macrophages and promote asthma progression." (PMID 36078171, 2022). "Although one of the causes of severe asthma with elevated MMP-12 levels can be attributed to viral infections such as RSV, MMP408 has potential as a therapeutic agent for MMP-12–dependent neutrophilic asthma induced by both RSV and non-RSV infection." (PMID 34703996, 2021). "Additionally, there were increases in the number of cells positive for ROCK1, ROCK2, TGF-β, MMP-9, MMP-12, and TIMP-1, and the percentages of isoprostane, biglycan, decorin, fibronectin, and collagen fibers, in the asthma group." (PMID 30979017, 2019). "AAMΦs express MMP12 and SPP1 (osteopontin) which have been shown to be increased in asthma." (PMID 25437859, 2014). "MMP-12 seems to be either redundant, not contributing to the overall asthma phenotype or has a synergistic (not additive) role in the process." (PMID 23390895, 2013). "If gp91phox is imagined to have a regulatory role in development of the asthma phenmotype, MMP12 seems to have a similar if not synergistic effect." (PMID 22216879, 2012). "Furthermore, MMP-12 has been suggested to regulate the expression of NOS2, which has been shown to be upregulated in the airway epithelium of patients with asthma and is the main producer of exhaled nitric oxide, which is a surrogate biomarker of eosinophilic airway inflammation." (PMID 33946872, 2021). "Composite asthma symptoms expressed in a more aggravated manner in both the KO (SKO and DKO) mice compared to WT indicating that some redundancy may exist in the response pathways of gp91phox and MMP-12." (PMID 23390895, 2013).
asthma (continued). "Thus, MMP-12 induction by inflammatory cytokines may be a potential pathophysiological mechanism by which ASMC mediate and facilitate inflammatory respiratory disorders such as asthma and COPD." (PMID 16359550, 2005).
pulmonary fibrosis (37 papers, 2006 to 2025). Chronic progressive interstitial lung disorder characterized by the replacement of the lung tissue by connective tissue, leading to progressive dyspnea, respiratory failure, or right heart failure. "MMP12 has been found to be pro-fibrotic during bleomycin-induced lung fibrosis, in line with our findings that elevated levels of MMP12 are associated with worse CPI." (PMID 32171287, 2020). "MMP-12 deficiency reduced myocardial fibrosis following myocardial infarction and angiotensin II infusion, liver, and lung fibrosis after Schistosoma mansoni infection and lung fibrosis after bleomycin infusion in mice." (PMID 32508810, 2020). "Gene polymorphism of uPAR, called UPAR rs344781, has been associated with increased risk of vascular injury in SSc, while gene polymorphism of MMP-12, named MMP-12 rs2276109, has been correlated with diffuse cutaneous SSc and pulmonary fibrosis." (PMID 28791304, 2017). "In fact, MMP-12 deficiency resulted in decreased inflammation and collagen deposition in Fas-L and bleomycin -induced lung fibrosis." (PMID 25302498, 2014). "In the present study, we observed that MMP-12 -/- mice responded to bleomycin administration by an increase of collagen content in lung tissue, which is the hallmark of pulmonary fibrosis." (PMID 16504062, 2006). "Moreover, as MMP-12 mRNA level is associated with strain-dependent susceptibility to develop bleomycin-induced pulmonary fibrosis, MMP-12 seems to be a relevant candidate for the determination of a pivotal proteolytic element in the development of pulmonary fibrosis." (PMID 16504062, 2006). "Our data demonstrate that PZQ can effectively suppress the transcriptional expression of TGF-β and MMP-12 in BLM-induced pulmonary fibrosis mice." (PMID 38355586, 2024). "The role of ptx3 in tissue remodeling is mainly related to turnover of fibrin-rich deposits at wound sites, and like MMP-12, ptx3 is also considered to have a role in the development of pulmonary fibrosis." (PMID 38702427, 2024). "Further, microarray data of lung samples from patients with idiopathic pulmonary fibrosis has shown a significant upregulation of MMP-12." (PMID 38702427, 2024). "Combined with elevated SASP mRNA expression (including Ccl2, Cxcl10, Ccl17, Mmp2, Mmp9, and Mmp12) in sorted macrophages after irradiation, we confirmed that senescent macrophages were partly contributed to lung fibrosis." (PMID 34023858, 2021). "Increased expression of TGF-β1, MMP-12, TIMP-1, CTGF, and fibronectin have been associated with the development of pulmonary fibrosis." (PMID 30087305, 2018). "Macrophages secrete MMPs, including MMP9 and MMP12, which participate in the pathogenesis of pulmonary fibrosis." (PMID 30250465, 2018). "Alveolar macrophages are important producers of MMPs, including MMP9 and MMP12, which are vital players in pulmonary fibrosis." (PMID 30250465, 2018). "MMP-12 reportedly has fibrotic activity in Fas-induced pulmonary fibrosis, and MMP-13 has shown similar activity in radiation-induced pulmonary fibrosis." (PMID 28936122, 2017). "The downregulated genes contained some mediators related to pulmonary fibrosis, such as Mmp12 and Mmp13." (PMID 28936122, 2017). "In a Schistosoma mansoni model of pulmonary fibrosis, Madala and colleagues demonstrate the intricate balance between MMP12 and MMP13 in modulating TH2-dependent lung and liver fibrosis." (PMID 27689529, 2016). "The role of MMP-12 during lung fibrosis has been studied in a number of different injury models, most of which attribute its role as being pro-fibrotic." (PMID 24713275, 2014). "Pro-fibrotic roles for MMP-12 were also found in models of pulmonary fibrosis generated by anti-Fas antibody (Jo2), which targets the tumor necrosis factor receptor, and infection with S. mansoni." (PMID 24713275, 2014).
pulmonary fibrosis (continued). "The development of pulmonary fibrosis in "fibrosis prone" (C57BL/6) mice was associated with prominent MMP-12 expression in lung, whereas MMP-12 expression was weak in lung tissue of "fibrosis resistant" (Balb/c) mice." (PMID 16504062, 2006). "According to our results, MMP-12 deficiency does not seem to be involved in TIMP-1 regulation and this would be consistent with the development of pulmonary fibrosis in MMP-12 -/- mice." (PMID 16504062, 2006). "The present study showed that MMP-12 -/- mice developed pulmonary fibrosis in a similar intensity to WT mice and the level of TIMP-1 protein and Timp-1 mRNA is similar in both strains." (PMID 16504062, 2006). "We therefore investigated the involvement of MMP-12 in the development of bleomycin-induced pulmonary fibrosis." (PMID 16504062, 2006). "Additionally, some studies have shown that loss of MMP-12 can protect mice from smoke-induced lung disease and FAS-induced pulmonary fibrosis." (PMID 38355586, 2024). "MMP12 degrades extracellular matrix components, participates in tissue remodeling processes, and is involved in acute and chronic inflammatory diseases, such as pulmonary fibrosis." (PMID 37491214, 2023). "However, other authors consider MMP-12 as a repressor of myofibroblast differentiation and lung fibrosis since mmp12-null mice showed an enhanced fibrotic response in bleomycin-induced PF compared with WT mice." (PMID 35805895, 2022). "Fibrosis-related genes include Col1a1, Acta2, Fn1, and Tgfb1 gene, and senescence-related genes composed of Cdkn2a, Tnf, Serpine1, Ccl2, Mmp10, and Mmp12 gene, all of which reflected the intensity of lung fibrosis and senescence events in lung tissue and pulmonary fibroblasts." (PMID 35662697, 2022). "MMP-12 has a key role in the development of TGF-β1-induced lung fibrosis." (PMID 35805895, 2022). "We speculate that inhibition of MMP9 and MMP12 induced by blocking 4-1BB signaling attenuates CS-induced pulmonary fibrosis via lessening the maturity of TGF-β and the deposition of collagen type I. Future studies are needed to address this hypothesis." (PMID 30250465, 2018). "MMP12 has a pivotal role in TGF-β mediated pulmonary fibrosis." (PMID 29677166, 2018). "Notably, TGF-β has been reported to stimulate pulmonary fibrosis and inflammation through Bax/Bid/MMP-12 signaling axis." (PMID 27542203, 2016). "Importantly, MMP-12 is highly elevated in the serum and connective tissue of SSc patients and correlates with vascular damage and the severity of skin and pulmonary fibrosis." (PMID 25302498, 2014). "Therefore, even though Th2 cytokine IL-13 has been involved in bleomycin-induced pulmonary fibrosis, IL-13-induced injury model seems to follow different pathways, including different participation of MMP-12." (PMID 16504062, 2006). "Importantly, MMP-12 was increased in the serum, alveolar macrophages and dermal inflammatory infiltrates in SSc patients, and its expression correlated with the severity of skin and lung fibrosis." (PMID 32508810, 2020). "Expression of fibrosis-related factors such as transforming growth factor beta (TGF-β1), matrix metalloproteinase 12 (MMP-12), tissue inhibitor of metalloproteinases-1 (TIMP-1), connective tissue growth factor (CTGF), and fibronectin, have been associated with the development of lung fibrosis." (PMID 30087305, 2018). "In our current study, we found that the level of MMP-12 significantly increased in BLM-induced pulmonary fibrosis mice, while treatment with PZQ was able to decrease the level of MMP-12." (PMID 38355586, 2024). "In our study, we examined some pro-fibrotic cytokines and found that in BLM-induced pulmonary fibrosis mice, the mRNA expression levels of TGF-β and MMP-12 were significantly elevated compared to the control group." (PMID 38355586, 2024).